AR (androgen receptor)
Diseases named in the same sentence as AR in open-access papers (continued):
Sharing a sentence is not in itself a finding about the gene and the disease.
prostate carcinoma (continued). "One study found that quercetin, a naturally occurring poly-phenol found in fruits and vegetables, reduced AR-SV and AR-FL expression through mitigating AR synthesis and, when used in combination with enzalutamide, was able to improve sensitivity in enzalutamide resistant prostate cancer cells." (PMID 36430245, 2022). "In prostate cancer, fatostatin suppresses cell proliferation and colony formation in both androgen-responsive or -insensitive cancer cells and causes G2/M cell cycle arrest and cell death, which is mediated by the blockade of the SREBP-regulated metabolic pathway and AR signaling network." (PMID 35912181, 2022). "In addition to imaging the ER and PR, a recent study demonstrated the feasibility and potential utility of imaging the androgen receptor (AR) in breast cancer, using the agent 18F-16β-18F-fluoro-5α-dihydrotestosterone, an agent that has been more widely tested in prostate cancer." (PMID 35729608, 2022). "Since upon disease onset almost all prostate cancers are androgen-dependent and require active androgen receptor (AR) signaling for their survival, the primary treatment approach has for decades relied on inhibition of the AR pathway via androgen deprivation therapy (ADT)." (PMID 35954292, 2022). "Consequently, the systematic targeting of full‐length AR in prostate cancer deserves attention." (PMID 34919781, 2022). "We further wanted to assess if the degradation of GATA2 also occurred in prostate cancer cells that rely on GATA2 for proper AR transcriptional function, or if GATA2 degradation may be a mechanism of protection from AR activity/differentiation in basal-like prostate epithelial cells." (PMID 35203681, 2022). "Hence, gene expression inhibition for androgen-synthesizing enzymes, by pomegranate polyphenols, could be a promising niche to address androgen-independent prostate cancer and AR up-regulation in the human subclass." (PMID 35566182, 2022). "Indeed, an association between high AR expression and growth-inhibition by SPA in prostate cancer models has been observed, begging the question of whether high AR activity is necessary for prostate cancer sensitivity to SPA." (PMID 36194476, 2022). "There is growing evidence, however, that β-catenin activation may occur through cues other than those involved in Wnt signaling, for example, the epidermal growth factor receptor (EGFR) in melanoma and the androgen receptor (AR) in prostate cancer, which was found to be a target of Wnt." (PMID 36497192, 2022). "Indeed, a recent study found that SARMs with potent growth-suppressive activity in prostate cancer activated the transcriptional activity of AR in a manner highly concordant to that of steroidal androgens, although effects on innate immune signaling were not reported in this study." (PMID 36923279, 2022). "Androgen deprivation therapy (ADT) is a common practice for the treatment of advanced prostate cancer (PCa) since its discovery by Huggins and Hodges in 1941, which involves surgical castration such as bilateral orchiectomy or chemical castration such as inhibition of androgen receptor (AR)." (PMID 35853851, 2022). "Thus, the physical interaction between rs6152 and an enhancer may play a role in the regulation of AR gene expression during prostate cancer progression." (PMID 35176995, 2022). "However, the influence of taxanes on androgen receptor signaling has been extensively observed and studied in the field of prostate cancer and provides additional understanding about the impact of taxane-induced microtubule dysfunction and sex-specific mechanisms of toxicity." (PMID 35884386, 2022).
prostate carcinoma (continued). "Therefore, treatments urgently need to be identified for AR-CRPC prostate cancers." (PMID 35453603, 2022). "Androgen receptor (AR) plays an important role in the occurrence and development of prostate cancer, and when it is activated by androgen, it can regulate the expression of downstream target genes, thus promoting the progression and metastasis of prostate cancer." (PMID 35814454, 2022). "This assumption was based on the observations that strong AhR ligands degraded AR in the LNCaP prostate cell line and that two other compounds, namely Icaritin and Carbidopa, which could activate AhR, suppressed prostate cancer via AhR-mediated degradation of AR." (PMID 36613955, 2022). "Data from this study provide multiple lines of scientific evidence demonstrating a critical role of AR signaling in stromal Gli1-lineage cells in supporting prostate epithelial cell tumorigenesis, leading to the development of different therapeutic strategies for treating advanced prostate cancer." (PMID 36323713, 2022). "Therefore, it has been shown that CaMKK2 is a target gene of AR in prostate cancer." (PMID 35409187, 2022). "A more recent study showed that the reprogrammed AR cistrome observed in mCRPC coincides with sites already bound by FOXA1 in normal and primary tumor tissue, further supporting a model where FOXA1 pre-marks a cancer-associated AR cistrome to facilitate prostate cancer progression." (PMID 36212399, 2022). "Moreover, our results provide further insights into the complex nature and multi-targeted therapeutic regimens that may be required to prolong the clinical benefit of next-generation AR antagonists in men with advanced, life-threatening prostate cancer." (PMID 35302608, 2022). "Interestingly, when we examined data from a previously published prostate cancer cohort, we found that AR expression negatively correlated with the expression of CDKN2B-AS1 in the normal prostate, and this correlation was completely dependent on the reference allele, but not the risk allele." (PMID 34513844, 2021). "Furthermore, GR can take the place of AR in antiandrogen-resistant prostate cancer cells." (PMID 34137734, 2021). "Besides, TPD52 might up-regulate the PSA an acknowledged downstream target gene of the androgen receptor which showed TPD52 mediated the tumor growth of prostate cancer was related to signals of androgen." (PMID 34099820, 2021). "Our data suggest that elevated levels of CCM1 can potentiate both ligand-dependent and ligand-independent AR signaling in the TME through the upregulation of YAP/TAZ signaling and that the resultant increase in AR signaling may also be important for progression to advanced prostate cancer." (PMID 33807895, 2021). "Therefore, our results suggest that the bioactive constituent of Aloe perryi extracts could serve as a targeted therapy for estrogen receptor α positive breast cancer or androgen receptor prostate cancer, which warrant further research and investigations." (PMID 34070945, 2021). "Additionally, PSA could be involved in the pathogenesis of prostate cancer by interacting with the androgen receptor target gene and stimulating oxidative stress in prostate cancer cell." (PMID 34299909, 2021). "Although it is tempting to hypothesize that the cellular switch into neuroendocrine, neuron-like phenotype is driven by AR, it is necessary to remember that at the final stage of differentiated NEPC, the prostate cancer cells have been reported to completely lack AR expression." (PMID 33572108, 2021). "Considering the low androgen levels in the adult brain compared to prostate cancer, we speculated that in contrast to prostate cancer, where androgens are the main drivers of cell proliferation, AR-mediated glioblastoma cell proliferation involves androgen-independent AR signaling." (PMID 34681618, 2021).
prostate carcinoma (continued). "In prostate cancer, loss of REST is associated with the emergence of the most aggressive form of the disease, NEPC, featuring its known characteristics, notably the loss of AR signaling, and induction of genes related to neuroendocrine differentiation, such as CHGA, a target gene of REST." (PMID 33572108, 2021). "A previous study revealed that AR could upregulate TWIST1 via ETV1 in prostate cancer." (PMID 33510354, 2021). "In AR-positive cells, a higher expression of miR-17-92a is observed compared to AR-negative cells and ectopic expression of AR could enhance the expression of miR-17-92a cluster in AR-negative prostate cancer cells while knockdown of AR decreased miR-17-92a expression in AR-positive cells." (PMID 33540707, 2021). "Therefore, ER in breast cancer could be involved in LAT1 regulation, as reported in AR of prostate cancer." (PMID 34503187, 2021). "In addition, SPOP might regulate androgen (AR) signaling way and SPOP down-expression led to the activation of AR signaling exerting oncogenic effect in prostate cancer." (PMID 34838022, 2021). "Our findings may provide a novel mechanism of AR reactivation in prostate cancer." (PMID 34295814, 2021). "Interestingly, three major subgroups of genomic subcomplexes of AR interaction partners were identified, where FOXA1 and HOXB13, known transcription factors interacting with AR and affecting the AR cistrome in prostate cancer, dictate selective gain of function for AR action." (PMID 34638309, 2021). "Work from us and others has shown that old age, comorbidities such as diabetes and hypertension, behavioral factors like smoking, and molecular factors like androgen receptor signaling and TMPRSS2 may contribute to the increased risk of COVID-19 for prostate cancer patients." (PMID 33915795, 2021). "Research is still lacking for small molecules that ortho- or allosterically interact with androgen receptors, as several other AR-targeted new drugs need to be investigated (such as RNA-based therapies), most of them for prostate cancer, although bladder cancer might also benefit from these." (PMID 33919565, 2021). "Because most treatments for prostate cancer target androgen receptor (AR) signaling, aberrations affecting this drug target are likely to emerge following the development of castration-resistant prostate cancer (CRPC), and it is conceivable that such aberrations may play a role in drug resistance." (PMID 34071114, 2021). "Thus, the development of an MLK1 inhibitor, either as a monotherapy or in combination with current AR-targeting agents, may provide a promising strategy for treating multiple types of prostate cancer." (PMID 34439974, 2021). "Limitations: Our study does not include the treatment history, such as chemotherapy or androgen receptor axis-targeted therapies, so we could not study the association or impact of that on COVID-19-positive prostate cancer patients." (PMID 33915795, 2021). "Moreover, in the same cell line, AR resumed by FOXC2 silencing can induce a massive reduction in self-renewal potential and stem cell proprieties, features previously linked to AR independence and prostate cancer progression." (PMID 33420371, 2021). "Therefore, AR therapy is one of the main means of prostate cancer treatment." (PMID 35342388, 2021). "The linkage of these AR gene-coded circRNAs to the differential effects on the cell invasion of prostate cancer (PCa) vs. bladder cancer (BCa) in response to androgen-deprivation therapy (ADT) with the antiandrogen Enzalutamide (Enz) treatment (ADT-Enz), however, remains unclear." (PMID 34127806, 2021). "In addition to reduced nuclear AR, bergamottin also lowers total AR expression which may be further contributing to growth inhibition, as AR is known to be the driver of prostate cancer growth." (PMID 34570813, 2021).
prostate carcinoma (continued). "We summarize clinical evidence supporting that information on a prostate cancer’s genomic composition may inform on its level of androgen receptor action, which may facilitate choice for the most effective first-line therapy and ultimately improve prostate cancer treatment plans overall." (PMID 34439101, 2021). "Thus, targeting AR has been considered a therapeutic option for the treatment of prostate cancer." (PMID 35069196, 2021). "Androgen-deprivation therapy (ADT) via targeting androgens/androgen receptor (AR) signals may suppress cell proliferation in both prostate cancer (PCa) and bladder cancer (BCa), yet its impact on the cell invasion of these two urological cancers remains unclear." (PMID 34127806, 2021). "In addition, the emergence of prostate cancer that lacks AR expression accelerates its malignancy." (PMID 34068627, 2021). "The AR-mediated regulation of LAT1 and ASCT2 is of clinical importance as inhibition of these transporters hampers prostate tumour growth and their increased expression provides opportunities for non-invasive diagnostic imaging and disease monitoring in patients with prostate cancer." (PMID 34262149, 2021). "The action of androgens is mediated via the androgen receptor (AR), a ligand-activated transcription factor and member of the steroid hormone nuclear receptor family, which mediates androgen signaling by binding to androgen response elements (AREs) in both normal prostate tissue and prostate cancer." (PMID 34359624, 2021). "Previous studies of prostate carcinoma-derived primary spheroid cultures have reported a potential alteration of the molecular biomarker pattern that may include a decline in both AR gene activity and the expression of AR-driven prostate biomarkers." (PMID 34581895, 2021). "Substances that can modify the androgen receptor pathway in humans and animals are entering the environment and food chain with the proven ability to disrupt hormonal systems and leading to toxicity and adverse effects on reproduction, brain development, and prostate cancer, among others." (PMID 33652992, 2021). "Thus, the modulation of AR expression or its signaling may control the development of prostatic hyperplasia or prostate cancer." (PMID 34202665, 2021). "Furthermore, for patients with metastatic AR-dependent prostate cancer innovative combination therapies that co-target multiple driver genes simultaneously may lead to increased patient survival." (PMID 34326322, 2021). "Moreover, this leads to the premise that simultaneous downregulation of KLF4 with increased AR levels could indicate a less favorable prostate cancer prognosis." (PMID 33640491, 2021). "The risk allele diminishes androgen receptor (AR) occupancy, is associated with decreased H3K27ac levels, and downregulates the expression of VPS53, FAM57A, and GEMIN4, and the knockdown of VPS53, FAM57A, and GEMIN4 in prostate cancer cells results in an increase in cell viability." (PMID 33919522, 2021). "Thus, in TNBCs, AR plays an oncogenic role similar to that observed in prostate cancer." (PMID 34680352, 2021). "In particular, we found that PROTAC compound 13b could successfully demonstrate a targeted degradation of AR in AR-positive cancer cells and might be a useful chemical probe for the investigation of AR-dependent cancer cells, as well as a potential therapeutic candidate for prostate cancers." (PMID 33926033, 2021). "The CTC counts obtained with CellCollector could also be tested in metastatic castration-sensitive prostate cancer patients (mCSPC) as biomarkers for evaluation of the treatment with androgen-receptor-axis-targeted (ARAT) therapy compared with docetaxel to improve the outcome in mCSPC patients." (PMID 34357036, 2021).
prostate carcinoma (continued). "Consistent with this hypothesis, we observed that growth of AR-dependent prostate cancer cells (LNCaP), as well as AR-independent prostate cancer cells (C4-2B, PC-3, DU145, and LNCaP-LN3), was significantly inhibited upon depletion of SETD1A in these cell lines using siRNA or shRNA." (PMID 32629770, 2020). "In addition, the treatment of early stage and advanced prostate cancer cells with the selective SPHK2 inhibitor, ABC294640, induces a reduction in Myc and androgen receptor (AR) expression, and this is associated with significant inhibition of growth, proliferation, and cell cycle progression." (PMID 32260399, 2020). "Thus, metastatic prostate cancer cells to the bone retain luminal features and likely AR signaling proficiency, which may make them relatively more responsive to AR modulators compared to visceral metastases." (PMID 31936761, 2020). "Early anti-androgen treatment may be helpful in AR-dependent prostate cancer." (PMID 32972001, 2020). "Harmol and harmine hydrochloride are inverse agonists of benzodiazepine receptors that are involved in steroid synthesis, so it is also possible that their inhibition at the peripheral level could account for the inhibition of AR-mediated prostate cancer cell growth." (PMID 32560058, 2020). "Furthermore, tumor suppressor miRNAs such as Let-7 and miR-30b, -30d, -200 family or oncogenic miRNAs such as miR-141, -125b, -21 and -32, target the AR and play a role in the progression of prostate cancer to the more aggressive, metastatic castration-resistant stage." (PMID 32645914, 2020). "Thus, we examined whether blocking AR signaling could impair the infection ability of SARS-CoV-2 in the AR-positive LNCaP prostate cancer cell line, which we found to be permissive to infection with isolated SARS-CoV-2 virus." (PMID 33310900, 2020). "Thus, PSF may regulate the AR signaling pathway at multiple steps, which lead to prostate cancer progression." (PMID 32106418, 2020). "However, in prostate cancer miR-182 seems to be associated with AR signaling and not with neuroendocrine differentiation." (PMID 32645914, 2020). "Taken together with the hormone independent growth of PMEPA1-depleted xenograft of LNCaP cells in nude mice, it is implied that the PMEPA-b isoform might contribute to progression into castration resistance stage via manipulating AR signaling in prostate cancer cells." (PMID 32842649, 2020). "Interestingly, acute treatment of multiple AR-proficient prostate cancer cell lines with any of the AR inhibitors was sufficient to modulate DECR1 expression and transient silencing of DECR1 potentiated the effect of enzalutamide in C4-2 cells, a CRPC derivative of LNCaP." (PMID 32427840, 2020). "However, whether modulation of AR signaling may alter transcriptome of prostate cancer cells via alternative splicing remains largely unexplored." (PMID 32820253, 2020). "Interestingly, down-regulation of PIK3R1 in prostate cancer has been linked to reciprocal negative feedback between the AR and PI3K signaling cascades, and PIK3R3 upregulation has been linked to prostate hyperplasia." (PMID 32630372, 2020). "Androgen receptor can be activated through the binding of endogenous androgens, such as testosterone and its metabolite dihydrotestosterone (DHT), to regulate the expression of a series of key downstream genes, causing uncontrolled proliferation of prostate cells and triggering prostate cancer." (PMID 33094102, 2020). "Therefore, using RT-PCR we demonstrated that genomic inhibition and pharmacological inhibition of AR may induce similar splicing pattern, within a subset of genes in prostate cancer cells." (PMID 32820253, 2020). "Moreover, we evaluated AR CN status at baseline and progression time points, but AR CN at first radiological evaluation after 3 months of therapy is needed, as it represents the most clinically significant time point, according to Prostate Cancer Clinical Trials Working Group 3 guidelines." (PMID 33072600, 2020).